KISS1 (KiSS-1 metastasis suppressor)
Diseases named in the same sentence as KISS1 in open-access papers (continued):
Sharing a sentence is not in itself a finding about the gene and the disease.
tumor (continued). "Tumor size, Kiss-1 expression in positive SLN and size of SLN metastasis were independently associated with NSLN metastasis (p<0.05)." (PMID 25111296, 2014). "Expression of Kiss-1 in positive SLN is correlated with decrease of Kiss-1 expression from tumor to positive SLN." (PMID 25111296, 2014). "In the multivariable logistic regression analysis, tumor size, expression of kiss-1 in positive SLN and the size of SLN metastasis were each associated with the likelihood of NSLN metastases." (PMID 25111296, 2014). "In that same report, we described the unexpected finding that KISS1 –>KP processing occurred outside of the tumor cells." (PMID 24454770, 2014). "More specifically, we focused on a select number of SATB1 target genes that are known to participate in tumorigenesis and metastasis (e.g. tumor/metastasis suppressors BRMS1, Kiss1, Claudin-1; tumor/metastasis promoters c-Abl, MMP3, ErbB2 and Snail)." (PMID 24260116, 2013). "Kiss1 gene was initially discovered as a tumour metastasis suppressor gene of melanoma cells in nude mice without affecting their tumorigenicity." (PMID 23696833, 2013). "Most of these studies have shown that the KiSS-1/GPR54 system is negatively correlated with tumor progression." (PMID 19154616, 2009). "In the same tumor, KISS1 was expressed differently in various pathological stages." (PMID 41523580, 2026). "As the tumor‐initiating capacity contributes to the metastasis of a primary tumor, the clone assay may suggest a role of KISS1 in cancer metastasis." (PMID 41523580, 2026). "Thus, several metastasis suppressors have been described, and among them, KISS1 raised our interest for its still controversial role in tumor metastasis." (PMID 41523580, 2026). "Furthermore, we explored the GTEx database to evaluate the difference in KISS1 expression between normal and tumor tissues." (PMID 41523580, 2026). "Furthermore, we explored the importance of KISS1 in the suppressive tumor microenvironment (STM) through the relationship between KISS1 expression and the infiltration level of MDSCs and Tregs." (PMID 41523580, 2026). "KISS1 has been reported to be a tumor metastasis suppressor in several cancer types." (PMID 41523580, 2026). "The activation of KISS1 can effectively reduce the motility and invasive ability of tumor cells." (PMID 40332793, 2025). "KISS1, as a key metastasis suppressor, is closely related to tumor progression." (PMID 40332793, 2025). "Moreover, KISS-1 is a potent inhibitor of tumor metastasis and plays a role in placentation; both processes involve angiogenesis." (PMID 37024487, 2023). "However, we also noted that our findings are inconsistent with some other studies, which have suggested that KISS-1 can also induce apoptosis in tumor cells." (PMID 37024487, 2023). "The development includes the radiolabeling of the NODAGA-KISS1-54 peptide by the positron emitter Gallium-68 (68Ga) and a preclinical evaluation of [68Ga]KISS1-54 in cell culture and tumor-bearing mice to assess its suitability as a PET radiotracer for molecular imaging." (PMID 38256878, 2023). "Activation of AhR by kynurenine has also been reported to inhibit the growth of tumor cells, promote cellular differentiation, and decrease the formation of hepatic and pulmonary metastases in mice through activation of the tumor suppressor gene KISS1." (PMID 33451095, 2021). "We can conclude that KISS1 expression was negatively correlated with the tumor size." (PMID 35117986, 2021). "Melatonin and Kiss1 were shown to be involved in tumor suppression." (PMID 32118379, 2020). "Kiss1 level was much higher in tumor-bearing than in healthy mice." (PMID 32118379, 2020). "Thus, in the tumor microenvironment, we should evaluate not only the expression of KISS1/KISS1R in surrounding cells, but also in additional regulation systems such as in the production of cytokines." (PMID 31336647, 2019). "In several types of tumors, KISS1 acts as a tumor suppressor gene." (PMID 31336647, 2019).
tumor (continued). "However, later, the involvement of KISS1/KISS1R in tumor development was demonstrated in several tumor types." (PMID 31336647, 2019). "Conversely, in triple negative breast cancer (TNBC) cells, which lack estrogen receptor (ER)α, progesterone receptor, and human epidermal growth factor receptor, KISS1 acts as a tumor promoter, whereas in ERα-positive breast tumors, the situation appears more complex." (PMID 31336647, 2019). "This could be a valid method to intervene on the block of metastatic development through the treatment with KiSS-1 that inducing tumor cell dormancy could block the metastatic process." (PMID 29760678, 2018). "Genomic studies suggest that KiSS-1/KiSS-1R expression might be different in the various stages of tumor development." (PMID 29760678, 2018). "Thus, KiSS-1 gene acts as a cancer suppressor gene and activation of Kp signaling cascade inhibits cancer cell invasion, metastasis formation, and tumor recurrence." (PMID 29662466, 2018). "Further studies have demonstrated that downregulation of KiSS-1 may be involved in the process of tumor invasiveness and metastasis." (PMID 30021598, 2018). "Decreased expression of KISS1/KISS1R in tumor tissues compared with normal." (PMID 30123188, 2018). "Thus, the possibility to keep tumor cells in a dormant state and obtain high survival through the use of exogenous KiSS-1 therapy has been suggested to represent an important goal for the treatment of tumor patients." (PMID 29760678, 2018). "KiSS-1 is widely regarded as a suppressor of tumor metastasis in various cancers." (PMID 28253891, 2017). "For example, it is found that high expression of KiSS1 can inhibit proliferation and invasion of tumor cells via lipofectin transfection of expression vector containing full-length KiSS1 complementary DNA (cDNA) into the tumor cell." (PMID 27287327, 2016). "Our results suggest that L. lactis is an ideal cell factory for secretory expression of tumor metastasis-inhibiting peptide KiSS1, and the KiSS1-producing L. lactis strain may serve as a new tool for cancer therapy in the future." (PMID 27287327, 2016). "KISS1 was recognized as a tumor metastasis suppressor and aroused our interest." (PMID 27145368, 2016). "Furthermore, through Human Tumor Metastasis PCR Array we discovered KISS1 was one of the downstream targets of SIRT1." (PMID 27145368, 2016). "The human tumor-metastasis inhibitor protein KiSS1 was successfully expressed in L. lactis." (PMID 27287327, 2016). "In this study, we evaluated whether L. lactis can be used as a cell factory to produce bioactive KiSS1 peptide and whether the secreted product has anti-tumor activity using the human colon cancer HT-29 as a model for in vitro experiments." (PMID 27287327, 2016). "The effect of Kiss-1 on MMPs related to tumour metastasis was also deleted by zymography." (PMID 25260785, 2014). "In summary, it is suggested Kiss-1 inhibits ERK activation and consequently reduces the enzymatic activity of MMP-9 caused by the degradation of NF-κB, which contributes to the suppression of tumour metastasis." (PMID 25260785, 2014). "Hypermethylation of KiSS1 is also correlated with high tumor grade and stage." (PMID 25272010, 2014). "KiSS1 is a tumor metastasis suppressor gene in several cancers." (PMID 25272010, 2014). "One possible explanation for the role played by Kiss-1 in cancer biology could be extrapolated from the relationship between Kiss-1 and matrix metalloproteinases (MMPs), whose significance in tumour invasion and metastasis formation is well known." (PMID 25260785, 2014).
tumor (continued). "The mechanism by which the KiSS-1/GPR54 system regulates tumor progression still remains unclear, although various studies have revealed the downstream signaling pathways activated by KiSS-1 gene product." (PMID 19154616, 2009). "In addition to the inhibition of tumor metastasis, KiSS-1 shows neuroendocrine activity and has a role in the gonadotropin-releasing hormone cascade, puberty, placentation, and reproduction, as shown by recent studies." (PMID 19154616, 2009). "Furthermore, we initially analyzed the potential PTMs of KISS1 within cells, which may affect the phenotype of tumor cells in a text‐dependent manner." (PMID 41523580, 2026). "Besides, we assessed the correlation between KISS1 expression and immune cell infiltration, immunosuppressive cells, and immune checkpoint genes, which may aid in immunotherapy for tumor metastasis." (PMID 41523580, 2026). "Therefore, combined with the fact that Kiss1 can affect Ca2+ signaling and mitochondrial β-oxidation in tumor biology, we propose that the Kiss1/GPR54 system in the skeletal muscle might have an implication for energy metabolism during exercise." (PMID 36231110, 2022). "In this respect, the epigenetic regulation of KISS1 in cancer deserves particular attention, as there is a presently unfulfilled need to identify the alternative pathways required for the expression of the tumor target molecules involved in the development of metastases." (PMID 31336647, 2019). "Finally, a role played by KiSS-1 in the dormancy of disseminated tumor cells and in the suppression of multiple organ metastases was described, representing the possibility of maintaining the tumor in an asymptomatic state." (PMID 29760678, 2018). "However, the precise function of KiSS-1 in tumor metastasis is still unclear." (PMID 28253891, 2017). "When the expression of genes affecting the metastasis or suppression of tumor cells was investigated, urotensin-II increased MTA-1 and ESR1 expression and decreased Kiss1 expression." (PMID 42287353, 2026). "They identified AQP5, KiSS-1, FZD7, AURKB, UBE2C, and PTTG1 as overexpressed in recurrent CNs, suggesting these genes play a role in tumor progression." (PMID 39066950, 2024). "The researchers observed that AHR activation significantly upregulated the expression of kisspeptin 1 (KISS1), a molecule known to inhibit tumor metastasis." (PMID 37943609, 2023). "The relative expression of KISS1, FREM2, and ECM1 were in the pyramidal pattern, implying that maximal expression was in the tumor area." (PMID 38062443, 2023). "The high expression of UHRF1 inhibits a variety of tumor suppressor genes, such as BRCA1, KISS1, and MEG." (PMID 35656341, 2022). "Consistently, in pancreatic and ovarian cancer, KISS1/KISS1R was found to be upregulated in initial phases of cancer development, thus acting as a tumor suppressor." (PMID 31336647, 2019). "Recently, we demonstrated that KISS1/KISS1R mRNA and protein expression was upregulated in primary TNBC tumor biopsies compared to healthy breast tissue." (PMID 30123188, 2018). "Since we were able to detect exogenous kisspeptin-54 and endogenous KISS1 in MDA-MB-231 cell lysates, we conclude that KISS1 levels were too low to be detected in these tumor and normal breast samples." (PMID 28422142, 2017). "Tumor suppressors including KiSS1, BRCA1, p16, MEG3 and PPAR-gamma are known to inhibit the tumor cell migration and invasion." (PMID 28584306, 2017). "There is a growing appreciation for the notion that metastasis-regulating genes, such as KISS1, BRMS1, NME1 or SMAD4, exert their effects at both the tumor and TME level." (PMID 29050279, 2017). "Results revealed a punctate distribution of KISS1 and a robust localization of KISS1R and AXL in tumor cells." (PMID 28422142, 2017). "The current study is the first study to analyze the impact of tumor and positive SLN Kiss-1 expression for NSLN involvement." (PMID 25111296, 2014).
tumor (continued). "The expression of Kiss-1 correlated significantly with Dukes classification, TNM staging, tumour stage and lymph node involvement." (PMID 25260785, 2014). "More specifically, knockdown of plakoglobin in MCF-7 cells resulted in the increased mRNA and protein levels of the tumor/metastasis promoters c-Abl, Snail, ErbB2 and MMP3 and the decreased levels of tumor/metastasis suppressors BRMS1, Kiss1 and Claudin-1." (PMID 24260116, 2013). "Seven clinicopathological factors were involved in the multivariate logistic regression model: menopausal status, tumor size, ER, PR, HER2, nm-23 and Kiss-1." (PMID 23012578, 2012). "Many genes, such as nm23, KAI1, KISS1, MKK4, BrMS1 and so on, have been identified to have relations with the tumor metastasis." (PMID 17784942, 2007). "We then tested the possibility that knocking down KISS1 could statistically reduce the metastatic capacity of MDA‐MB‐231 cells, which implied that the EMT process of tumor cells was influenced, to some extent, by KISS1." (PMID 41523580, 2026). "WT or KISS1‐knockdown showed the same tumor volume, which indicated that KISS1 did not affect tumor growth." (PMID 41523580, 2026). "The mesenchymal cells demonstrated a decrease in expression of tumor suppressor and negative cell cycle regulator RB1 and tumor and metastasis suppressor KISS1 while OVCAR had an increase in expression of these two genes." (PMID 41028875, 2025). "Kisspeptin-1 (KISS1) functions as a metastasis suppressor by inhibiting metastasis without affecting primary tumor growth." (PMID 38774408, 2024). "Thus, further [68Ga]KISS1-54 circulation was highly reduced, resulting in the relatively low absolute tracer accumulation in the KISS1R-positive LNCap tumor." (PMID 38256878, 2023). "The Kiss1 gene was first identified as a metastasis suppressor gene in melanoma, which suppresses metastasis without affecting the formation of primary tumor." (PMID 38256878, 2023). "In concordance with the tumor suppressor role reported for miR-199b in other tumor types, miR-199b downregulation was found to contribute to CRC progression through the modulation of the SIRT1/CREB/KISS1 pathway via SIRT1 activation." (PMID 32731550, 2020). "Finally, through in vivo ectopic tumor formation experiments, we further confirmed that miR-506 targets UHRF1 to inhibit the proliferation and invasion of CRC by the KISS1/PI3K/NF-κB signaling pathway." (PMID 31803739, 2019). "The KISS1 gene was named after Hershey’s chocolate kisses because it was initially isolated from human non-metastatic pigment tumours in Hershey (Pennsylvania, USA), and the “SS” represents “suppressor sequence”." (PMID 31399145, 2019). "KiSS-1 expression is also reported to suppress the metastatic potential of tumor cells but not tumorigenicity." (PMID 30021598, 2018). "KISS1 is an established tumour suppressor, discovered to be absent in metastatic cells but present in non-metastatic cells." (PMID 30602942, 2018). "The results of this study indicated a negative correlation between positive expression of KiSS-1 and tumor size, invasion, LNM stage, or TNM stage." (PMID 30021598, 2018). "Whether KISS1, KISS1R and fibulin-3 are expressed in the TNBC tumor microenvironment has yet to be determined." (PMID 30046386, 2018). "First, the lack of KISS1R expression in many tumor cell lines that can be metastasis suppressed by re-expression of KISS1 provided the first clue that autocrine signaling is not required for an anti-metastatic function." (PMID 24454770, 2014). "Furthermore, the mRNA and protein levels of tumor/metastasis suppressors BRMS1, Kiss1 and Claudin-1 were decreased in MCF-7-shPG cells relative to MCF-7 cells (bottom)." (PMID 24260116, 2013). "The expression of KiSS1 (metastin) has been reported to exhibit an inverse correlation with human tumor progression and metastasis, and is either reduced or absent in various types of cancers." (PMID 18328103, 2008).
tumor (continued). "In addition, the specificity of the [68Ga]KISS1-54 uptake into tumor cells was determined via the co-incubation of [68Ga]KISS1-54 with the nonradioactive KISS1-54 peptide in excess for 60 min." (PMID 38256878, 2023). "The NODAGA-KISS1-54 peptide was labeled by Gallium-68, and the stability of the resulting [68Ga]KISS1-54 evaluated in injection solution and human serum, followed by an examination in different KISS1R-expressing tumor cell lines, including HepG2, HeLa, MDA-MB-231, MCF7, LNCap, SK-BR-3, and HCT116." (PMID 38256878, 2023). "Located on the long arm of chromosome 1, KISS-1 is regulated by TXNIP, CRSP3, and TCF21 and is mainly expressed in tissues such as the placenta, kidney, pancreas, and hypothalamic arcuate nucleus, where it exerts vital roles in the suppression of native tumor metastasis." (PMID 35875143, 2022). "While not fully confirmed, this suggests that Kiss-1 signaling in cancer cells may act both as a growth factor (via increases in the autocrine production of GnRH), and a tumor suppressor (independently of GnRH)." (PMID 30777054, 2019). "Besides, a possible explanation for the role played by KiSS1 in cancer biology can be extrapolated from the correlation between KiSS1 and matrix metalloproteases (MMPs), particularly MMP-9 and MMP-2, whose significance in tumor invasion and metastasis formation is well known." (PMID 29721201, 2018). "The same inverse correlation with tumor stage and overall survival rate was also described for bladder cancer, where every tumor that had developed distant metastasis showed complete absence of KISS1 expression." (PMID 28207895, 2017). "KISS1 is a member of the still-expanding family of metastasis suppressors, which are defined by their ability to block metastasis without preventing primary tumor development." (PMID 27145368, 2016). "KISS1 is a gene that suppresses the metastasis of tumor cells without affecting tumorigenicity." (PMID 24979261, 2014). "Kiss-1 has a significant, and negative correlation with tumour metastasis and invasion." (PMID 25260785, 2014). "Conversely, genetic alterations that could enhance tumor metastasis but did not affect primary tumor growth were largely overlooked, until persistent investigators raised awareness of genes that selectively altered metastasis, such as nm23, KISS1 and BRMS1." (PMID 35164808, 2022). "In fact, it has been demonstrated that KISS1 and KISS1R expression in tumor cells is not sufficient, per se, to predict cancer development behavior." (PMID 31336647, 2019). "Regarding malignant tissues, it has been shown that the expression level of KiSS-1 had a negative correlation with Dukes staging, TNM (tumor, lymph node, and metastasis) staging, tumor size, and lymph node involvement." (PMID 29760678, 2018).